CD40 (CD40 molecule)
Diseases named in the same sentence as CD40 in open-access papers (continued):
Sharing a sentence is not in itself a finding about the gene and the disease.
tumor (continued). "Despite their relatively low affinity, these T cells may be useful components of the anti-tumor immune response, and priming self-reactive T cells may be the major mechanism by which radiation and anti-CD40 synergize." (PMID 30245691, 2018). "However, macrophage inhibition during IL-2/anti-CD40 immunotherapy in young mice led to tumor outgrowth and only 43% survival." (PMID 30459812, 2018). "The observation that anti-CD40 mAbs enable CD8+ T cell independent tumor cell killing, prompted the use of a fully humanized CD40 agonist mAb (CP-870.893) in a phase I clinical trial, showing that its combination with gemcitabine activates antitumor immune responses." (PMID 30233579, 2018). "The development of autoimmune vitiligo in mice treated with radiation and anti-CD40 underscores the fact that augmentation of T cell priming may induce priming of both autoreactive and tumor-reactive T cells." (PMID 30245691, 2018). "Moreover, we showed that dendritic cells were resistant to the anti-CD40 treatment and unable to stimulate anti-tumor responses." (PMID 29975708, 2018). "Regardless of age, IL-2/CD40 up-regulated CD25 on tumor-associated CD8+ T cells relative to PBS controls, this increase was more striking in young mice." (PMID 30560130, 2018). "IL-2/CD40 mostly did not alter young or elderly tumor-associated DC subset proportions, relative to untreated mice, with the exception of a small, but significant, increase in cross-presenting CD8α+CD11b− cDCs in elderly tumors." (PMID 30560130, 2018). "Nonetheless, IL-2/CD40 was less effective in elderly tumor-bearing mice, which could be attributed to an exacerbated suppressive environment in elderly TDLNs." (PMID 30560130, 2018). "As CD40 monotherapy was insufficient to eliminate tumor burden, we speculated that therapeutic synergy could be maximally achieved by combination treatment with radiation to induce immunogenic cell death." (PMID 30400835, 2018). "Stimulation of the CD40 pathway to initiate anti-tumor immunity is a promising alternative." (PMID 28427434, 2017). "Yet, within the PDAC tumor microenvironment, CD40 could override the demand of the CD4+ helper cells for activating cytotoxic CD8+ T cells." (PMID 28753978, 2017). "However, the difference was not significant in other maturation markers such as CD80 and CD40 probably because implanted tumor cells induced DC maturation." (PMID 28060726, 2017). "CD40 was shown to be one of the key regulators conferring T cell-dependent anti-tumor immunity." (PMID 28753978, 2017). "Several studies have been proposed, in which enhancing CD40 activity with its agonists may improve T-cell-dependent (macrophages activation and tumour stroma destruction) and independent immune responses and consequently induce cancer regression." (PMID 28640192, 2017). "This may particularly avail the use of immunoadjuvants like GM-CSF or anti-CD40, which enhance the recruitment and activation of APCs within the tumor." (PMID 28447024, 2017). "Finally, activation of macrophages in a genetically engineered mouse model of pancreatic cancer with an agonist monoclonal CD40 antibody synergizes with chemotherapy (CTX) to induce tumour regression." (PMID 28210073, 2017). "Mice treated with the CD40 aptamer-shRNA chimera showed higher tumor infiltration of lymphocytes." (PMID 28325295, 2017). "In this regard, increased secretion of CD40 from epithelial cancer cells may regulate their own properties within the tumor mass in an autocrine or paracrine fashion." (PMID 29285252, 2017). "Accordingly, the direct tumoricidal effects depend highly on the CD40 expression of the tumor." (PMID 29387053, 2017). "In addition, certain chemotherapies can synergize with anti-CD40 and TLR agonists to change tumor-associated macrophages from pro-tumor M2 phenotype to anti-tumor M1 phenotype, resulting in anti-tumor effects in murine melanoma and neuroblastoma models." (PMID 28216575, 2017).
tumor (continued). "Treatment of tumor-bearing mice with anti-CD40 mAb led to increased activation of CD11c+ dendritic cells in the tumor draining lymph node, while sunitinib treatment reduced vessel density and decreased accumulation of CD11b+Gr1+ myeloid derived suppressor cells." (PMID 27385210, 2016). "CD40 is expressed on a wide variety of cells, including DCs, macrophages, monocytes, B cells, endothelial cells and some tumor cells, but the main therapeutic activity is considered to be through the licensing of DCs to activate an antitumor cytotoxic T-cell response." (PMID 27385210, 2016). "To determine the efficacy of long-term combination therapy of anti-CD40 mAb and sunitinib, we treated B16.F10 tumor-bearing mice with the combination, the monotherapies or control for 5 weeks (35 days) and sacrificed mice when the tumors reached a volume of 1 cm3." (PMID 27385210, 2016). "Therefore, we investigated if combining anti-CD40 mAb therapy with sunitinib treatment affects the activation status of conventional DCs (cDCs) (B220−CD11b+/−CD11c+) in the tumor draining lymph node." (PMID 27385210, 2016). "Furthermore, our study showed that HMGB1 in the supernatant of tumor cells treated with PV-10 was responsible for the up-regulation of CD40 expression on BM-derived DCs and for the increased ability of DC to stimulate T cell activation." (PMID 27177220, 2016). "Also in preclinical models of ACT, agonistic CD40 antibodies promote tumor-specific T cell expansion and enhanced anti-tumor activity." (PMID 27656185, 2016). "Another approach is to limit the recruitment of circulating monocytes at tumor sites by interfering with their response to chemoattractants, or to re-activate macrophage cytotoxic potential with agonist anti-CD40 antibodies, TLR agonists or low dose irradiation." (PMID 27191500, 2016). "Therefore, anti-CD40 mAb therapy was administrated locally on day 10 and 13 after tumor injection, and sunitinib was given by oral gavage on days 10-13." (PMID 27385210, 2016). "A number of recent studies have reported the importance of CD40+ MDSC in tumor growth." (PMID 26462153, 2015). "In addition, administration of CpG ODN 1826 with agonist anti-CD40 antibody in combination with vincristine, Cy and doxorubicin chemotherapy produced anti-tumor effects mediated by effector M1 macrophages." (PMID 26082836, 2015). "Thus, CD40-stimulating mAbs (e.g., CD-870873) have direct anti-tumor activity and induce tumor antigen-specific T cell responses." (PMID 29546098, 2015). "The outcomes of CD40 ligation on tumor cells are ambivalent depending on the models studied." (PMID 25763299, 2015). "Interestingly, one of the LGSC samples with CD40-negative tumor cells contained multiple CD40-positive lymphoid follicles, which are likely the cause of its positivity in western blot." (PMID 26313915, 2015). "A phase I study investigated the maximum tolerated dose (MTD), safety, pharmacodynamics, immunological correlatives, and anti-tumor activity of CP-870,893, a CD40 agonist antibody, when administered in combination with gemcitabine in patients with advanced PDAC." (PMID 26266422, 2015). "Indeed, activation of APCs in vivo with an antibody to CD40 has been shown to overcome CD4+ T cell anergy in some tumor models." (PMID 25875653, 2015). "In particular, the role of CD40 in generating T cell responses provides the possibility of eliciting effective anti-tumor immune responses because CD40 on APC can deliver co-stimulatory signaling for the activation of CD8+ cells directly without the activation of CD4+ helper T cells." (PMID 25992978, 2015). "CD40 is a tumour necrosis factor receptor superfamily member that is expressed on antigen-presenting cells (APCs) such as dendritic cells (DC), B cells, monocytes and some tumour cells." (PMID 25651850, 2015).
tumor (continued). "Our study will address the disadvantages of agonistic CD40 mAb in tumour therapy and may provide novel therapeutic strategies, as well as explain the pathogenesis of non-small cell lung cancer (NSCLC)." (PMID 25651850, 2015). "Whether the outcome of anti-CD40 antibody therapy is pro- or antitumorigenic will most likely depend on the immunogenicity of the tumor." (PMID 25682197, 2015). "Thus, we focused on the effect of CD40 stimulation in the production of immune modulatory molecules from tumor cells." (PMID 25992978, 2015). "In one hand, CD40 ligation promotes anti-tumor immune surveillance through a variety of mechanisms including antigen-presenting cell activation, restoration of malignant cell immune recognition, activation of tumoricidal-infiltrating macrophages, immunostimulatory cytokine production." (PMID 25763299, 2015). "In addition, CD40 agonists destruct the tumor stroma by targeting macrophages and also reestablish the tumor immune surveillance in PDA." (PMID 25897428, 2015). "Along with the uptake of tumor-associated antigens and presentation in the context of MHC molecules, professional APCs are further required to provide lymphocyte costimulation, such as through expression of the B7 molecules (CD80 and CD86) or CD40." (PMID 26483791, 2015). "The CD40-activation by itself already slowed tumor growth and prolonged survival." (PMID 25682197, 2015). "A further understanding of the mechanisms of CD40 signalling pathway-mediated inflammatory E-cadherin + DC differentiation in innate immunity and the tumour microenvironment may provide novel therapeutic strategies and insight into the pathogenesis of NSCLC." (PMID 25651850, 2015). "CD40 ligation also induces tumor growth arrest and sensitization to apoptotic signals." (PMID 25763299, 2015). "In agonistic CD40 antibody-mediated inflammatory responses, a novel subset of E-cadherin + dendritic cells (DCs) has been identified, and little is known about the role of these DCs in tumour immunity." (PMID 25651850, 2015). "Focal, positive staining for CD40 was observed in tumor cells from two of five LGSC samples." (PMID 26313915, 2015). "Noteworthy here is the use of a CD40− tumor model, which confirms the hypothesis that DCs are the most likely targets for the agonistic anti-CD40 antibodies." (PMID 25682197, 2015). "Concerns include cytokine release syndromes, autoimmune reactions, thromboembolic syndromes, hyperimmune stimulation leading to activation-induced cell apoptosis or tolerance and tumour angiogenesis, possibly as a result of the CD40-dependent activation of tumour endothelial cells." (PMID 25651850, 2015). "CD40 is expressed at high levels during tumorigenesis by tumor infiltrating MDSC." (PMID 26462153, 2015). "However, T-cell responses and tumor protection can be rescued by additional stimuli, e.g. by CD40 ligation or low dose UV-B irradiation." (PMID 25025233, 2014). "In this work we showed that in vitro VSSP treatment of both tumor-induced MDSCs and BM-MDSCs was sufficient to increase not only CD11c marker, typically associated with DCs, but also the co-stimulatory molecules CD40 and CD86." (PMID 24829762, 2014). "In addition, the levels of CD40 expression on the tumor-derived MDSCs decreased gradually from 71.67±5.42 to 3.56±0.99% (mean ± SEM), and that of the splenic MDSCs decreased from 26.53±0.82 to 9.05±0.43% (mean ± SEM)." (PMID 25009656, 2014). "However, significant downregulation of CD40 expression on the MDSCs was observed with tumor progression (P<0.05)." (PMID 25009656, 2014). "Furthermore, tumor-infiltrating MDSCs exhibited significantly higher CD40 expression levels than the spleen-derived MDSCs (P<0.05)." (PMID 25009656, 2014). "Since tumor progression affects the differentiation of MDSCs towards a suppressive phenotype, the downregulation of CD40 may correlate with the functional state of the MDSCs." (PMID 25009656, 2014).
tumor (continued). "Notably, a significant decrease in the level of CD40 expression was observed in addition to an increased number of MDSCs during tumor progression." (PMID 25009656, 2014). "CD40 is also expressed by a wide variety of cells, such as neurons, dendritic cells, microglia, B cells, macrophages, keratinocytes, endothelial cells, thymic epithelial cells, fibroblasts and various tumor cells." (PMID 25038616, 2014). "For example, Cho and Celis have demonstrated that a vaccination approach using synthetic peptides representing CTL epitopes, TLR agonists and anti-CD40 antibodies was able to generate large quantities of high-avidity antigen-reactive T cells capable of killing tumor cells." (PMID 24664420, 2014). "The current study demonstrated that CD40 mediates the accumulation of MDSCs via the induction of MDSC apoptosis, therefore, CD40 may present a novel target for decreasing MDSC levels in the tumor environment." (PMID 25009656, 2014). "CD40 is a crucial member of the group of co-stimulating molecules, orchestrating both humoral and cell-mediated immune responses, and is closely related with tumor invasion and metastasis." (PMID 24885116, 2014). "Downregulation/degradation of IκB as a part of the classical NFκB pathway activation has been described earlier.Additional important molecules for T cell/tumor communication are CD40, a costimulator of the TNF-R family, the adhesion molecule CD54 (LFA-1) and HLA class I antigens." (PMID 24885059, 2014). "Notably, a marked correlation was identified among MDSC accumulation, CD40 expression and tumor progression." (PMID 25009656, 2014). "It has been reported that CD40 mutant alters partial epitope of CD40 and has a different ability to combine with antibodies combining with wild-type CD40, indicating that CD40 mutant might play an important role in tumor development." (PMID 24885116, 2014). "A proposed strategy therefore is a combination of infusion of antibodies against CD40 in order to stimulate the secondary lymph node resident macrophages to migrate into the tumor tissue with IFN-γ to effectively reprogram tumor-induced M2-like macrophages into activated IL-12 producing M1 cells." (PMID 25192022, 2014). "Further studies should aim to elucidate whether this approach can be used to improve the anti-tumor efficacy and safety profile of CD40 activation in vivo." (PMID 24741998, 2014). "Several studies have also suggested that cancer-mediated thrombin generation by interaction between tumor cell CD40 and platelet-derived sCD40L is involved in tumor cell growth, motility, and angiogenesis through activation of gene transcription that promotes tumor metastasis and angiogenesis." (PMID 24745825, 2014). "Furthermore, as seen with the M12 cell line, CD40 ligation of some tumor cells can lead to cell death." (PMID 25324844, 2014). "However, after exposure to MF, both the population of CD11c+CD40+ DC (n = 10, p<0.05) and tumor infiltrating CD11c+ DC (n = 9, p<0.01) were significantly increased." (PMID 24278103, 2013). "They found that DCs were refractory to stimulation with the combination of LPS, IFN-γ, and anti-CD40 antibody, but tumor-induced DC paralysis could be reverted by a combination of CpGs and an anti-IL-10R antibody." (PMID 24339824, 2013). "Agonistic triggering of CD40 holds considerable promise as an anticancer therapeutic strategy and likely will trigger both direct antiproliferative and/or proapoptotic signaling in CD40-positive tumor cells as well as induction of antitumor T-cell immune responses." (PMID 23840967, 2013). "The effect of copper lowering on CD40 expression by tumor vessels is as yet unknown and further studies are required." (PMID 24013775, 2013). "An interesting molecule that may control CD40L+CD4+ T cell adhesion to endothelium is CD40 which can be expressed at higher levels by tumor endothelial cells relative to endothelia in normal tissues." (PMID 24013775, 2013).
tumor (continued). "In regard to a CTL-mediated tumor response, the induction of a Th1 response is crucial since the interaction of Th1 cell with DCs renders the DCs themselves capable for the activation of naïve CD-8+ T-cells by CD40 and CD40-L interaction." (PMID 23087898, 2012). "CD40 agonist antibody CP-870,893 can achieve substantial regression of tumours in some patients with inoperable pancreatic binding antibodies may bind to epitopes distinct from those involved in the natural CD40-CD40L interaction." (PMID 23125850, 2012). "Importantly, mice immunized with the CD40-targeted Ad5-huPSMA and Ad5-IFNγ demonstrated the greatest inhibition of tumor growth when challenged with RM-1-PSMA cells compared with the other groups." (PMID 23056548, 2012). "Since CD40 and C54 mediate activation and adhesion of immune cells, their lower expression on tumor cells may diminish NK cell binding to tumors and cytotoxicity." (PMID 23316193, 2012). "CpG-ODN synergized also with an agonist anti-CD40 mAb to revert TAM displaying anti-tumor activity." (PMID 24213109, 2011). "For instance, CD40 signaling in endothelial cells results in less apoptosis and increased proliferation, which may promote tumor growth through angiogenesis." (PMID 21912605, 2011). "Clinical reagents that activate CD40 have been developed for systemic use and have shown clinical promise, but these agents do not necessarily drive T cell responses in vivo owing to restrictive features of the tumor microenvironment." (PMID 21904611, 2011). "Thus, it is probable that the rs1800686 AA genotype contributes to breast carcinogenesis by lowing CD40 levels on immune cells to suppress the anti-tumor responses." (PMID 21912605, 2011). "However, measurable immune responses and control of tumor growth were achieved only by an adoptive transfer of antigen-specific transgenic T cells and co-administration of anti-CD40, Flt3, GMCSF and/or CpG." (PMID 21379572, 2011). "The aim of this study was to determine whether tumor RNA-transfected CD40-activated B cells could safely induce anti-tumor immunity and impact the natural history of spontaneous NHL in dogs after remission induction with chemotherapy." (PMID 21904611, 2011). "In addition, CD40 ligation protects human and murine DCs from tumor-induced apoptosis by inducing expression of anti-apoptotic proteins from the Bcl-2 family." (PMID 19591684, 2009). "Taken together, these findings suggest that the combination of CP-870,893 and CpG ODN 2006 represents a practical - and available - clinical approach to test the hypothesis that dual CD40/TLR9 activation in vivo can promote tumor immunity in patients." (PMID 19906293, 2009). "Because expression of CD40 on DCs, as well as CD40-mediated DC function are suppressed during tumor progression, its up-regulation by nontoxic chemotherapy should support the development of antitumor immunity in tumor-bearing hosts." (PMID 19591684, 2009). "Their more recent studies showed that tumor antigen plus agonistic anti-CD40 antibody combined with a TLR7 agonist reduced B16F10 lung metastases in mice, though the treatment began only four days after the intravenous injection of tumor cells, rather than being tested on established tumors." (PMID 19812695, 2009). "Stimulation of CD40 or Toll-Like Receptors (TLR) has potential for tumor immunotherapy." (PMID 19812695, 2009). "Recently, it has been suggested that activation of the CD40/CD40L pathway may enhance the pro-coagulant activity of tumour cells through up-regulation of tissue factor expression." (PMID 19400944, 2009). "The relevance of CD40-dependent signaling in tumor development is also emphasized by the observation that the oncogenic properties of the EBV protein LMP-1 are due to its ability to hijack part of the CD40 cascade." (PMID 17331231, 2007).